HPR (haptoglobin-related protein)
Description:
Primate-specific plasma protein associated with apolipoprotein L-I (apoL-I)-containing high-density lipoprotein (HDL). This HDL particle, termed trypanosome lytic factor-1 (TLF-1), mediates human innate immune protection against many species of African trypanosomes. Binds hemoglobin with high affinity and may contribute to the clearance of cell-free hemoglobin to allow hepatic recycling of heme iron.
Synonyms: A-259H10.2
Tractability: Antibody: UniProt places it where antibodies can reach, with high confidence; its Gene Ontology location is reachable by antibodies, with high confidence; UniProt predicts a signal peptide or a membrane-spanning region.
Gene: Protein-coding gene on chromosome 16 (72,063,148 to 72,077,246, forward strand). Ensembl gene ENSG00000261701.
Subcellular location: Secreted
Subcellular location (Human Protein Atlas): Vesicles; Predicted to be secreted
Pathways (Reactome):
Vesicle-mediated transport: Scavenging of heme from plasma
Gene Ontology:
Molecular function: hemoglobin binding; serine-type endopeptidase activity
Biological process: zymogen activation
Cellular component: blood microparticle; extracellular exosome; spherical high-density lipoprotein particle; extracellular region
Genetic constraint (gnomAD): Loss-of-function variants: 26 observed, 22.96 expected, observed/expected ratio (o/e) 1.13, 90% interval 0.83 to 1.57. The upper end of that interval is the gene's LOEUF score, 1.57, which puts it in group 6 of 6, group 1 being the genes least tolerant of losing a copy. Missense variants: 434 observed, 407.82 expected, observed/expected ratio (o/e) 1.06, 90% interval 0.98 to 1.15. Synonymous variants: 166 observed, 159.45 expected, observed/expected ratio (o/e) 1.04, 90% interval 0.92 to 1.18.
Homologues: Orthologues: rabbit HP (81% identical), dog DHODH (77% identical), mouse Hp (76% identical), rat Hp (76% identical), tropical clawed frog cfi (20% identical), Drosophila melanogaster CG31266 (16% identical), Drosophila melanogaster CG31267 (15% identical). Paralogues in human: HP (91% identical), C1S (32% identical), C1R (31% identical), C1RL (26% identical), F7 (23% identical), F10 (22% identical), KLKB1 (22% identical), F9 (21% identical), HGFAC (20% identical), F12 (20% identical), F11 (19% identical), CFI (18% identical), and 4 more.
Diseases named in the same sentence as HPR in open-access papers:
HPR is named in the same sentence as 33 diseases in open-access papers, as found by Europe PMC text mining. Sharing a sentence is not in itself a finding about the gene and the disease. The quoted sentences say what the papers report.
breast carcinoma (5 papers, 2008 to 2022). "HPR is a high-affinity hemoglobin-binding plasma protein that has been shown to have an association between its expression, breast cancer malignancy, and recurrence." (PMID 34944967, 2021). "Mutations in HPR have been documented in the literature as predictors of recurrent breast cancer." (PMID 27124395, 2016). "HPR, PKLR and PLAU have been reported to be overexpressed in breast cancers and esophageal squamous cell carcinoma." (PMID 35327967, 2022).
anthrax (2 papers, 2024 to 2025). "In B. anthracis, deletion of PTS proteins (HPr and Enzyme I) results in decreased atxA transcription and anthrax toxin production indicating the crucial role of PTS in anthrax virulence." (PMID 39998073, 2025).
human African trypanosomiasis (2 papers, 2012 to 2014). A parasitic disorder caused by protozoa of the Trypanosoma brucei species. "The geographical distribution of the HPR duplication allele overlaps the region where the pathogen causing chronic human African trypanosomiasis, Trypanosoma brucei gambiense, is endemic." (PMID 24005574, 2014). "TLF-1 and -2 are both capable of lysing the protozoan parasite Trypanosoma brucei which causes sleeping sickness in nonprimate mammals, with the HPR product acting as a ligand for, and thus guiding the lytic complex to, the parasite surface." (PMID 22433445, 2012). "The HPR duplication shows a slight, non-significant undertransmission to human African trypanosomiasis-affected children of unaffected parents in the Democratic Republic of Congo." (PMID 24005574, 2014).
Insulin resistance (2 papers, 2023 to 2024). Increased resistance towards insulin, that is, diminished effectiveness of insulin in reducing blood glucose levels. "In addition, six loci were linked to insulin resistance, type 2 diabetes, or reduction in HbA1c levels in type 2 diabetes (APOB, HPR, TM6SF2, KSR2, JMJD1C, and SLCO1B1)." (PMID 38532495, 2024).
lymphoma (2 papers, 2011 to 2021). A malignant (clonal) proliferation of B- lymphocytes or T- lymphocytes which involves the lymph nodes, bone marrow and/or extranodal sites. "In particular, an increase of the 21 kDa haptoglobin-related protein (Hpr) (which was the same protein identified in the whole saliva of our patient) has been reported in the serum of patients with malignant lymphoma, with advanced disease and "B" symptoms." (PMID 22047044, 2011).
melanoma (2 papers, 2023 to 2024). A malignant, usually aggressive tumor composed of atypical, neoplastic melanocytes. "Three proteins were commonly identified using the three algorithms as relevant in classifying EVs derived from patients with a melanoma diagnosis compared to those from healthy controls: specifically, Proteoglycan 4 (PRG4), Apolipoprotein C4 (APOC4) and Haptoglobin-Related Protein (HPR)." (PMID 39405606, 2024).
colorectal cancer (1 paper, 2021). A primary or metastatic malignant neoplasm that affects the colon or rectum. "Only three upregulated genes (APOC1, CYP2E1, HPR) were significant in term of prognosis, suggesting that these three genes could be associated with prognosis in colorectal cancer patients." (PMID 34081622, 2021).
iron deficiency (1 paper, 2025). "Upregulation of haptoglobin (HP) and haptoglobin-related protein (HPR), both of which bind free hemoglobin for hepatic heme iron recycling, occurred in UC but not CD, and this may represent a compensatory response to selectively minimize iron deficiency in UC but not CD." (PMID 40244226, 2025).
liver disease (1 paper, 2012). "Genes of inflammation and immunity (CD276, CDH6, GCKR, HNF1A, HPR, ITGA1, RORA, and STAT4) have been shown to be expressed in liver disease patients." (PMID 22530132, 2012).
myeloid leukemia (1 paper, 2022). A clonal proliferation of myeloid cells and their precursors in the bone marrow, peripheral blood, and spleen. "A function of HP and HPR in myeloid leukemia is yet to be determined." (PMID 36230605, 2022).
ovarian carcinoma (1 paper, 2018). A malignant neoplasm originating from the surface ovarian epithelium. "The common acute phase proteins HP, HPR, HPX, and SERPINA all showed significant increases with ovarian cancer." (PMID 30598658, 2018). "Peptides and/or phosphopeptides of common plasma proteins such as HPR, HP, HPX, and SERPINA1 showed increased observation frequency and/or precursor intensity in ovarian cancer." (PMID 30598658, 2018). "In agreement with the literature, peptides from many common proteins including acute phase response proteins such as Haptoglobin (HP), Haptoglobin Related Protein (HPR), Alpha Anti Trypsin (SERPINA1) and others were more frequently observed in ovarian cancer samples." (PMID 30598658, 2018).
infection (7 papers, 2013 to 2021). The state of being infected such as from the introduction of a foreign agent such as serum, vaccine, antigenic substance or organism. "These mice produce detectable levels of the TLF proteins (APOL1 and HPR) for at least 3 days post infection (Day 2- peak time of TLF production)." (PMID 34559857, 2021). "In this work we explored the role of HPr during infection using transgenic mice expressing the human transferrin that allows meningococcal growth by providing both iron and carbon sources." (PMID 27655040, 2016). "Here we show that in the hyper-invasive MC58 strain, the HPr plays an important role in meningococcal survival during infection especially in blood, which is most likely through enhancing the degradation of C3b to subvert complement activation." (PMID 27655040, 2016). "In the interaction of HDL with T. brucei, HDL is named trypanolytic factor (TLF), because endocytosis of certain HDL subspecies, which contain haptoglobin-related protein (Hpr, TLF-1) and apolipoprotein L-I (Apo L-I, TLF-2), causes lysis of T. b. brucei and protects mammalian hosts from infection." (PMID 25276058, 2014). "Haptoglobin (HPR) expression is known to be increased in inflammation, infection, and cancer." (PMID 23372690, 2013). "N. meningitidis uses a limited range of carbon sources during infection, such as glucose, that is usually transported into bacteria via the phosphoenolpyruvate (PEP):sugar phosphotransferase system (PTS), in which the phosphocarrier protein HPr (encoded by the ptsH gene) plays a central role." (PMID 27655040, 2016).
cancer (6 papers, 2013 to 2024). A tumor composed of atypical neoplastic, often pleomorphic cells that invade other tissues. "This was also found in our cohort with however too small sample size to rely on (10/19 hypopharynx cancer patients with hPR)." (PMID 25920604, 2016). "PKP1, as a HPR gene, has been documented to exhibit aberrant expression in various cancers." (PMID 38515846, 2024).
tumor (5 papers, 2021 to 2022). "The in vitro anti-tumor efficacy of GD2-SIL-HPR was studied through cell proliferation experiments, which demonstrated that this formulation significantly inhibited NB cell proliferation compared to HPR, either free or encapsulated in untargeted liposomes." (PMID 34577553, 2021). "It appeared that APOC1 expressed at the highest level, followed by CYP2E1 and HPR in all tumor stages." (PMID 34081622, 2021). "Finally, the expression of HPR genes in single-cell sequencing was analyzed, and the results also confirmed that most of HPR genes were highly expressed in tumor cells." (PMID 36120466, 2022).
HPR also shares sentences with these, for which no sentence is quoted: COVID-19 (3 papers); Alzheimer disease (1); bacteremia (1); bacterial pneumonia (1); brain cancer (1); endothelial dysfunction (1); esophageal squamous cell carcinoma (1); hepatoma (1); Hyponatremia (1); leukemia (1); metabolic disease (1); neurological disease (1); Obesity (1); polycystic kidney disease (1); polyp (1); Sepsis (1); trypanosomiasis (1); tuberculosis (1); type 2 diabetes (1).